MASP2 (MBL associated serine protease 2)
Diseases named in the same sentence as MASP2 in open-access papers (continued):
Sharing a sentence is not in itself a finding about the gene and the disease.
COVID-19 (continued). "The MASP-2 inhibitor narsoplimab was associated with rapid and sustained reduction of circulating endothelial cell counts and serum IL-6, IL-8, CRP, and lactate dehydrogenase (LDH) in six patients with COVID-19 on mechanical ventilation, correlating with clinical improvement." (PMID 34924021, 2021). "In addition to providing pathogenic insight, our research could direct the re-purposing of existing therapeutic agents that target lectin pathway activity, such as the MASP-2 inhibitor Narsoplimab, to clinical trials of COVID-19." (PMID 33995410, 2021). "As such, individuals with high levels of anti-MASP2 may be protected from serve COVID-19." (PMID 34930107, 2021). "Using immunohistochemistry for complement factors C1q, MASP-2, C3c, C3d, C4d, and C5b-9 we investigated the involvement of the complement system in six kidney biopsies with acute kidney failure in different clinical settings and three kidneys from autopsy material of patients with COVID-19." (PMID 33584662, 2020). "Interestingly, in tubuli from COVID-19 biopsies we observed a higher collectin 11 mRNA expression compared to 1 year biopsies, HUS and ATI controls and MASP-2 deposition in some of the COVID-19 cases, indicating that activation of the lectin pathway in COVID-19 was not restricted to lung or skin." (PMID 33584662, 2020). "Indeed, experimental evidence suggests that coronavirus N protein:MASP-2 interaction leads to an uncontrolled activation of the complement lectin pathway, and, recently, complement was postulated as a target for therapy in COVID-19 patients." (PMID 32943538, 2020). "While deposition of MASP-2, C4d, C5b-9 and MBL was shown in lung tissue from COVID-19 patients, increased complement activation product levels were observed in patient sera from SARS-CoV-2 infected individuals." (PMID 37051252, 2023). "In accordance with these findings, MASP-2, as well as MBL, C4a, C4, and C5b-9, accumulate in lung tissue of COVID-19 patients." (PMID 33729332, 2021). "FB deposits were also seen in COVID-19 lungs and are consistent with activation of the alternative pathway, whereas MBL and MASP-2 were hardly detectable." (PMID 34440207, 2021). "Thus, COVID-19 patients have an operative recognition through the lectin pathway, which might be a prerequisite for the described complex formation of the virus’ N protein with MASP-2, one of the serine proteases in the lectin pathway." (PMID 32943538, 2020). "Additionally, in peritubular capillaries and renal arteries, MASP-2 was detected in only 22% 2/9 of cases from patients with COVID-19 respectively, but could otherwise only be detected in renal arteries of HUS and in peritubular capillaries in HUS and ATI groups and not at all in the Ctrl biopsies." (PMID 33584662, 2020). "A recent preprint study reported that the paraformaldehyde-fixed lung tissue from patients who died of COVID-19 revealed strong expression of complement components MBL, MASP-2, C4a, C3, and the terminal MAC C5b-9, suggesting LP complement hyper-activation occurred in the lungs of COVID-19 patients." (PMID 33811541, 2021). "Furthermore, the comparative analysis revealed no statistically significant variation in MASP-2 serum levels between individuals recovered from COVID-19 (n = 347) and uninfected control subjects." (PMID 40869200, 2025). "Using immunohistochemistry we investigated deposition of complement factors C1q, MASP-2, factor D (CFD), C3c, C3d and C5b-9 as well as myeloperoxidase (MPO) positive neutrophils and SARS-CoV-2 virus particles in lungs and kidneys from 38 patients who died from COVID-19." (PMID 35237273, 2022). "The SARS-CoV-2 N:MASP-2 association was also confirmed in lung tissue sections from COVID-19 victims but not cancer patients by an in situ proximity ligation assay (PLA), and the N protein:MASP-2 complexes (red fluorescent spots) were mainly distributed in pulmonary epithelial cells." (PMID 36100602, 2022).
COVID-19 (continued). "We detected increased plasma H-ficolin, MASP-2 and MAp19 in severe compared to non-severe COVID-19." (PMID 33995410, 2021). "As first complement factor, we detected the glomerular deposition of MASP-2, a serine protease, that complexes with the lectin pathway initiators (MBL, ficolins, and collectins) and becomes activated upon binding to the lectin ligand and found it in 2/9 of the COVID-19 biopsies." (PMID 33584662, 2020). "Compared to non-severe COVID-19, samples from patients with severe COVID-19 had higher H-ficolin (p=0.02), MASP-2 (p=0.03), and MAp19 (p=0.03) levels." (PMID 33995410, 2021).
IgA nephropathy (8 papers, 2019 to 2025). "Narsoplimab is a human monoclonal antibody against MASP-2 that has been investigated for the treatment of patients with IgA nephropathy (NCT03608033)." (PMID 40283639, 2025). "Currently, several clinical trials are assessing the efficacy of selective complement inhibitors in IgA nephropathy, with promising results showing a reduction in proteinuria and inhibition of route-specific complement activation reported for CFB and MASP-2 inhibitors." (PMID 38046006, 2023). "These duplexes can be tested further in various mouse models of diseases involving MASP-1 and MASP-2 such as IgA Nephropathy and experimental pneumococcal meningitis to understand the contribution of liver MASP1 and MASP2 to disease pathology in conditions where LP activations has been implicated." (PMID 32153567, 2020).
colorectal cancer (7 papers, 2014 to 2023). A primary or metastatic malignant neoplasm that affects the colon or rectum. "It has been shown that MASP2 is also associated with the recurrence and survival rate of cancer (colorectal cancer in specific)." (PMID 24559495, 2014). "Furthermore, a CASZ1–MASP2 fusion transcript, detected in colorectal cancer, encodes an N-terminally truncated MASP2 controlled by the CASZ1 promoter." (PMID 38053207, 2023). "Furthermore, serum levels of MASP-2 have been associated with post-operative infections, recurrent cancer, and poor survival in colorectal cancer patients." (PMID 30532757, 2018). "A CASZ1-MASP2 fusion transcript was identified in colorectal cancer with 3′ overexpression of MASP2." (PMID 31481981, 2019). "In addition, MASP-2 levels have been linked to several diseases including schizophrenia, acute lymphoblastic leukaemia, non-Hodgkin lymphoma and colorectal cancer amongst others, suggesting a role for MASP-2 (downstream of lectin-glycan interactions) in human disease." (PMID 28894916, 2018). "Increased serum levels of MBL and MASP-2 were found in patients with colorectal cancer, which were not explained by genetic profiles." (PMID 30532757, 2018).
myocardial infarction (7 papers, 2018 to 2024). Gross necrosis of the myocardium, as a result of interruption of the blood supply to the area, as in coronary thrombosis. "Proteins involved in the complement and coagulation cascades, like MASP2, CRP, FCN3, and MBL2, were elevated, underlining the known importance of innate immunity and inflammation early in myocardial infarction." (PMID 39513871, 2024). "In a previous report, the peripheral levels of MASP-2 in patients with myocardial infarction were significantly lower than those in HCs, and the coronary levels of MASP-2 were negatively correlated with the myocardial necrosis marker." (PMID 35677590, 2022). "MASP-2 has been shown to be reduced in the peripheral blood of myocardial infarct patients as well as those in a coronary artery bypass grafting setting and MASP-2 levels correlated with an increase in a myocardial necrosis marker." (PMID 28894916, 2018). "This suggests that our TFPI D2–based MASP-2 inhibitors could be suitable for acute treatment of life-threatening disease conditions accompanied by IRI, such as myocardial infarct or stroke." (PMID 30952698, 2019).
thrombotic microangiopathies (7 papers, 2018 to 2025). "The therapeutic effect of anti-MASP-2 antibody Narsoplimab has been recognized in LP-activated thrombotic microangiopathies." (PMID 33811541, 2021). "Currently, only the MASP-2 inhibitor, narsoplimab, is being studied for thrombotic microangiopathies." (PMID 34069355, 2021). "In hematopoietic stem cell transplantation-associated thrombotic microangiopathy (HSCT-TMA), plasma MASP-2 levels are elevated versus healthy controls, and narsoplimab has been shown to reduce HSCT-TMA plasma-mediated endothelial damage in a tissue culture model." (PMID 38022610, 2023). "Interestingly, MASP-2 inhibitors improved endothelial cell damage in patients with thrombotic microangiopathy, who also presented high MASP-2 levels." (PMID 33729332, 2021). "The only clinically available MASP inhibitor is narsoplimab (Omeros and Lonza; Basel, CH), targeting MASP2, and was granted FDA Breakthrough Therapy and Organ Drug designations for thrombotic microangiopathies." (PMID 34069355, 2021).
Chagas disease (6 papers, 2012 to 2025). A parasitic infection caused by Trypanosoma cruzi. "MASP2 polymorphisms and haplotypes have been associated by us with susceptibility to Chagas disease and hepatitis C, and by others with bacterial infections after orthotopic liver transplantation and malaria." (PMID 23935922, 2013). "COLEC11 rs7567833G and MASP2 Chagas disease risk genotypes may act synergistically to increase the risk of developing CCC Chagas disease." (PMID 40297326, 2025). "Beside these differences in population structure, functional differences among the MBL2*B, C and D variants regarding MASP-2 coupling and serum concentration of low-mass oligomers may explain opposite association outcomes and should be further investigated in the context of Chagas disease." (PMID 26745156, 2016). "Increased T. cruzi loads in MBL−/− mice are strongly in accord with recent genetic studies showing that low-responser MBL and MASP-2 genotypes in humans are overrepresented among patients with Chagas’ disease and Chagas’ cardiomyopathy." (PMID 23139754, 2012). "A cohort study on 251 patients with Chagas disease in Brazil found that genetic variations in COLEC11 and MASP2 contributed to the pathogenesis of Chagas disease, which is characterized by dilated cardiomyopathy." (PMID 41155225, 2025). "Although recent genetic studies suggest an involvement of MBL/MASP2-associated pathways in Chagas’ disease, it is currently unknown whether MBL plays a role in host resistance to the intracellular protozoan Trypanosoma cruzi, the causative agent of Chagas’ disease." (PMID 23139754, 2012).
tuberculosis (6 papers, 2015 to 2021). A chronic, recurrent infection caused by the bacterium Mycobacterium tuberculosis. "Recent studies have discussed association of MASP2 gene polymorphisms and human diseases, such as RA, tuberculosis." (PMID 32677764, 2020). "Additionally, polymorphisms in MBL and MASP-2 genes were associated with the susceptibility of tuberculosis, showing possible gene–gene interactions." (PMID 33498555, 2021). "This study explores the association between MBL and MASP-2 gene polymorphism and their interactions and the susceptibility to tuberculosis (TB)." (PMID 25887173, 2015). "Genotype TC at rs2273346 and rs6695096 of MASP2 genes were more prevalent in the tuberculosis patients in Canada than the healthy controls." (PMID 32677764, 2020). "Previous studies were able to identify tuberculosis-associated variants in a few CTLR genes in different populations, such as for MRC2, MBL, or MASP2 in Chinese populations, DC-SIGN variants in African populations, and several variants of SPA-1, SPA-2, or MBL in diverse populations." (PMID 29515573, 2018). "Thus it indicated that MASP-2 may act as a immunomodulatory to promote macrophages and lymphocytes migrating to the lungs for the control of tuberculosis." (PMID 28536447, 2017). "In this study, we injected an adenoviral vector of encoding human MASP-2 (rAd-hMASP-2) into BCG-infected mice and evaluated the survival, examined the bacterial loads and immune response in the lung to assess the potential effect and mechanism on tuberculosis granulomas." (PMID 28536447, 2017). "However, the mechanism of MASP-2 on tuberculosis is unknown." (PMID 28536447, 2017).
leprosy (5 papers, 2013 to 2021). Leprosy is a chronic infectious disease affecting primarily the skin and peripheral nervous system. "Haplotype frequencies (% ± standard deviation) in Brazilian leprosy patients and controls, and association with MASP-2 and MAp19 concentration and the disease (adjusted effect ± standard deviation)." (PMID 23935922, 2013). "Instead, low MASP-2 levels generated by p.126L, p.377A and/or p.439H combined with the exon 5 flanking AG variants were associated with susceptibility to leprosy per se as well as with lepromatous disease." (PMID 23935922, 2013). "In this work, we investigated if MASP2 polymorphisms and MASP-2 or MAp19 levels in serum can play a role in the susceptibility to leprosy." (PMID 23935922, 2013). "The results lead us to suggest that, in contrast to MBL, low MASP-2 levels increase the susceptibility to leprosy in general and to lepromatous leprosy in particular." (PMID 23935922, 2013). "This may underly the opposite association results with MASP2*2B1-i: resistance with leprosy per se (as previously reported by and susceptibility to HBV infection per se." (PMID 33643280, 2020). "Both leprosy patients and Brazilian controls presented the described profile of MASP-2 levels according to the exon 5 flanking polymorphisms, but patients presented lower MASP-2 levels than controls (medians: 253 vs. 348 ng/mL, respectively, Mann-Whitney P = 0.0012, PBf = 0.0084)." (PMID 23935922, 2013). "For the MASP2 gene, we confirmed the previously published association of the MASP2*2B1-i haplotype (regardless of the intron 4 rs2273344–intron 5 rs9430347 AG or GA combinations) with resistance against leprosy per se (OR = 0.29 [95%CI = 0.10–0.82], P = 0.009)." (PMID 33643280, 2020). "In addition to low MASP-2, high MAp19 levels could play a role in leprosy pathogenesis, but the strong association with p.439H, which does not occur in the truncated protein, disfavors an important role for it." (PMID 23935922, 2013). "Low MASP-2 levels, as well as MASP2 polymorphisms associated with low MASP-2 production, were associated with increased susceptibility to leprosy." (PMID 32240160, 2020). "Minor allele frequencies (% ± standard deviation) in the Danish population, leprosy patients and controls, and association with MASP-2 and MAp19 concentration and the disease (adjusted effect ± standard deviation)." (PMID 23935922, 2013). "Both leprosy and malaria are intracellular infections associated with the same MBL and MASP-2 variants that disturb the lectin pathway of complement activation, nevertheless with opposite effects on the disease susceptibility." (PMID 23935922, 2013). "These associations were independent of demographic factors and did not increase susceptibility to leprosy per se, except MASP2*1C2-l." (PMID 33643280, 2020). "For long time, MASP2 had been considered the main effector of the lectin pathway of the complement and has been associated with several infectious diseases including Hepatitis C virus (HCV) infection, Pseudomonas infection, leprosy, as well as TB." (PMID 29515573, 2018). "We also evaluated MASP-2 levels in further 46 leprosy patients and 69 Brazilian controls." (PMID 23935922, 2013). "Surprisingly, we found that genetically-defined low MASP-2 levels do not mimic the protective association found between MBL and M-ficolin deficiencies and leprosy." (PMID 23935922, 2013). "MASP2 genotypes and MASP-2 levels might be used as biomarkers to predict disease progression in leprosy." (PMID 23935922, 2013). "We haplotyped 11 MASP2 polymorphisms with multiplex sequence-specific PCR in 219 Brazilian leprosy patients (131 lepromatous, 29 borderline, 21 tuberculoid, 14 undetermined, 24 unspecified), 405 healthy Brazilians and 291 Danish blood donors with previously determined MASP-2 and MAp19 levels." (PMID 23935922, 2013). "MASP2 genotypes and MASP-2 levels might thus be of prognostic value for leprosy progression." (PMID 23935922, 2013).
mastitis (5 papers, 2022 to 2025). Inflammation of breast tissue during lactation or postpartum due to an obstructed duct or infection. "The polymorphism G553A in MASP2 was found to be associated with mastitis resistance and lower milk SCC in Chinese Holsteins." (PMID 36911690, 2023). "It was shown how the polymorphisms of the MASP2 gene relate to mastitis and milk output in Chinese Holstein cattle." (PMID 37756095, 2023). "Candidate genes identified in Angus include the neurotrophic receptor tyrosine kinase 2 (NTRK2) that has been implicated with the sire conception rate in Holstein cattle, and MBL associated serine protease 2 (MASP2) was associated with mastitis and milk production in Chinese Holstein cattle." (PMID 40424241, 2025). "The MASP2 gene plays an important role in innate immunity and creates resistance to infections of the mammary gland and is therefore widely studied for its link with mastitis in dairy cattle." (PMID 36911690, 2023). "Here, C1, MBL, MASP1, and MASP2 were downregulated in mastitis." (PMID 36335251, 2022).